IL10 (interleukin 10)
Diseases named in the same sentence as IL10 in open-access papers (continued):
Sharing a sentence is not in itself a finding about the gene and the disease.
tumor (continued). "Various mechanisms through which intact tumor cells suppress DC functions have been described, including cytokines (e.g., TGF-β, IL-10, and vascular endothelial growth factor), ceramide, and other tumor-derived lipids." (PMID 26795730, 2016). "Tregs accumulate and expand in the tumor microenvironment and produce excessive interleukin 10 (IL-10) and TGFβ1." (PMID 27270649, 2016). "Tregs maintain homeostasis in immunity; our data suggest that Foxp3+ Tregs obtained from IL-10−/− B16/F10 tumor-bearing mice become unstable after antigen stimulation depriving them of Foxp3+ expression." (PMID 27075020, 2016). "The impairment of tumor growth after treatment with anti-Nrp-1 confirms our finding that IL-10 plays a central role in this process." (PMID 27075020, 2016). "Type 1 (IFN-γ, IL-12) and type 2 (IL-4, IL-10) cytokines were measured next in supernatants collected from tumour lysate-pulsed DCs co-cultured with syngeneic naїve T-cells." (PMID 26795765, 2016). "Mounting evidence supports a potent inhibitory role of IL-10 in tumor carcinogenesis, angiogenesis and metastasis." (PMID 27489033, 2016). "Investigators identified increased tumor infiltration with PD-1high Bregs which produced IL-10 upon interaction with PD-L1 or anti-PD1 antibody." (PMID 27437104, 2016). "This favorable profile stands in contrast to the typical anti-inflammatory and tissue-regenerative activities of hAAT, which include elevated IL-10 levels and further emphasizes the possibility that serum hAAT is distinct from tumor environment hAAT." (PMID 28003813, 2016). "The tumor volume decreased significantly in IL10−/− B16/F10 mice treated with anti-TGF-β Ab compared with WT mice." (PMID 27075020, 2016). "In lung carcinoma, tumor-derived miR-214 reduced PTEN expression (phosphatase and tensin homolog) and promoted the expansion of Treg cells, and miR-214-induced higher secretion of IL-10 in Treg cells and promoted tumor growth." (PMID 27999575, 2016). "In sharp contrast, differentiation of CD4+ T cells into IL-10-secreting regulatory T cells inhibits adaptive immune responses and thereby promotes tumor immune evasion." (PMID 27853652, 2016). "We previously reported that antitumor B cells directly kill tumor cells via the Fas/FasL pathway and are regulated by IL-10." (PMID 27528023, 2016). "In some cases, IL-10 improves the metastatic capability of lung tumor cells by increasing the vascular density in the primary tumor and increasing the resistance of lung tumor cells to apoptosis by activating STAT3 pathway." (PMID 27445423, 2016). "It has been reported that B cell-deficient mice exhibit enhanced antitumor immunity, possibly due to the reduction of IL-10 produced by B cells when the CD40 expressed on B cells interacts with CD40L expressed by tumor cells." (PMID 27136203, 2016). "Treg cells secret anti-inflammatory cytokines such as IL-10 and facilitate in escaping of immunosurveillance in the growing tumor." (PMID 27120805, 2016). "Significantly more mature CD11b+CD11chi (mDC) cells were detected in IL-10 knockout tumor-bearing mice compared with WT mice (mDC, left)." (PMID 27075020, 2016). "Upregulation of IL10 in cancer is probably caused by genetic polymorphism in the IL10 promoter, suggesting that an increase of IL10 is essential for tumor development." (PMID 26956044, 2016). "Conversely, tumor cell-derived HMGB1 was shown to suppress CD8+ T cells antitumor immunity through the induction of IL-10-producing Tregs." (PMID 27917371, 2016). "Generally known as an immunosuppressive cytokine, IL-10 is found at high levels in a variety of neoplasms." (PMID 26973839, 2016). "IL10, an anti‐inflammatory cytokine, secreted mostly by macrophages and T regulatory cells, has been shown to regulate T‐cell response and tumor immunity." (PMID 26833741, 2016). "Gal-1 also contributes to the infiltration of IL-10-producing Treg1 cells to promote the tumor evasion." (PMID 26933916, 2016).
tumor (continued). "Previous studies revealed that IL10 promotes cancer development by inhibiting anti-tumor immune responses." (PMID 26956044, 2016). "Incubation of MCF-7 cells with supernatants of MΦ previously treated with chelators did not have any effect on cellular proliferation, whereas supernatant of IL-10-stimulated MΦ significantly enhanced tumor cell proliferation." (PMID 27806101, 2016). "Herein, the transcripts coding IFN-γ and IL10 were quantitated in the skin lesions of the infected hamsters by RT-qPCR, and the results are expressed as fold increase relative to uninfected paws." (PMID 25569338, 2015). "IL-10-positive xenografts showed significantly increased tumor growth fractions and increased angiogenesis." (PMID 26425658, 2015). "In this paper, we demonstrate the significance of IL-10 in regulating NK cell-induced differentiation of the tumor cells." (PMID 26697005, 2015). "TAMs, a macrophage population recruited and educated by tumor cells, which are therefore exposed to IL-10, TGF-β, M-CSF (monocyte colony stimulating factor) and other immunosuppressive stimuli, are more closely related to the M2 type." (PMID 26243145, 2015). "They include soluble factors such as transforming growth factor-β (TGF-β), interleukin 10, and galectins or suppressive cells found at the tumor site such as regulatory T cells, tolerogenic dendritic cells, or myeloid-derived suppressor cells." (PMID 26161423, 2015). "This is of interest, as several reports have shown that MDSCs produce IL-10, and IL-10 also has been shown to promote NK cell proliferation and cytotoxic activity against tumor cells." (PMID 26470881, 2015). "For example, it was shown that IL-10 can decrease proinflammatory cytokine expression or anti-tumor T cell responses." (PMID 26631117, 2015). "Recently, exogenous gene transfer of MMP-9 was shown to suppress tumours by increasing neutrophil infiltration into the tumour site, a process that enhances macrophage secretion of pro-inflammatory cytokines and decreases IL-10 production." (PMID 25588705, 2015). "IL-24 is the only IL-10 cytokine family member whose functions are regulated by PTMs, analogous to classical tumor suppressors." (PMID 26009991, 2015). "Taken together, these data illustrate the enigmatic role of IL-10-mediating tumor growth as well as suppression, the balance of which is greatly influenced by tumor biology and micro-environmental cues." (PMID 26217588, 2015). "In contrast, the anti-inflammatory cytokine IL-10 was detected at all ratios of DCs:JU77 tumor cells." (PMID 25886502, 2015). "As an inflammatory modulatory cytokine, IL–10 was reported to exert both anti-tumor and pro-tumor function." (PMID 26440936, 2015). "The presence of soluble decoy receptors like soluble TLR2 and TLR4 and the down-regulation of TLR expression by anti-inflammatory cytokines, such as TGF-β and IL-10 are the most likely functional mechanisms in the tumor environment." (PMID 25682197, 2015). "TAMs are a major component of the tumor stroma, which contribute to the evasion of tumors from immune control by producing immune-suppressive cytokines such as IL-10 and TGF-β." (PMID 26379663, 2015). "These cells in turn can suppress the activity of effector cells in the tumor microenvironment by the secretion of soluble molecules such as IL-10, IL-35 and TGF-β." (PMID 25682197, 2015). "Exposure of TAM to tumor-derived cytokines such as IL-4, IL-10, IL-13, and M-CSF is able to convert them into polarized type II or M2 macrophages with immune-suppressive activities resulting in tumor progression." (PMID 26441986, 2015). "IL–10 is an important immunosuppressive cytokine which is frequently elevated in tumor microenvironment." (PMID 26440936, 2015). "While IL-10 also plays a duplicitous role in tumor suppression and progression at tissues outside of the CNS, its biological actions in peripheral sites also differ in several important ways." (PMID 26217588, 2015).
tumor (continued). "VEGF and IL-10 secreted in the tumor microenvironment constitutively activate STAT3 signaling in DCs, leading to downregulation of MHC class II molecules and costimulatory molecules, preventing DC maturation." (PMID 26528286, 2015). "These authors provided evidence indicating that NK cells are a primary mediator of autophagy in tumor target cells by a mechanism involving cytokines (IL-10, IL-2, IFNγ) and that cell-to-cell contact strongly enhanced lymphocyte-mediated autophagy." (PMID 26441986, 2015). "The immunosuppressive microenvironment created by molecules such as TGFβ and IL10 polarizes tumor-infiltrating microglia/macrophages toward the M2 phenotype." (PMID 25978454, 2015). "IL–10 was generally known as an immunosuppressive cytokine which mainly promoted the proliferation and metastasis of tumor cells." (PMID 26440936, 2015). "Our results showed that tumor-exposed, lipid-laden iMoDCs increased production of the anti-inflammatory cytokine IL-10, suggesting skewing towards a tolerogenic profile." (PMID 25886502, 2015). "Composite results show that daily oral intake of celecoxib in tumor-bearing mice can lower the amounts of M-CSF, IL-6, IL-10, COX-2, and TGF-β gene expression in tumors of tumor-bearing mice." (PMID 26167490, 2015). "Many tumor-produced factors, such as IL-10, IL-6 and VEGF, activate STAT3 by efficient feed-forward mechanisms." (PMID 26512963, 2015). "IL-10, an anti-inflammatory cytokine, is a potent mediator of immunosuppression in the tumor microenvironment through inhibition of T cell activation." (PMID 26106384, 2015). "Tumor-derived cytokines such as IL-4, IL-10, IL-13, TGF-β, or prostaglandin E2 promote M2 generation and are correlated to poor prognosis in several human cancers." (PMID 26425658, 2015). "The amounts IL-10 gene expression in tumor tissues of tumor-bearing mice are statistically significantly lower in groups TM, TB, and TX when compared to group TC (P < 0.05)." (PMID 26167490, 2015). "Systemic injection of TLR2/6 agonist Pam2 lipopeptides has induced IL-10 production in mice models which prevented effective anti tumor immunity." (PMID 25965265, 2015). "A low expression level of TGF-beta, IL-10, ICAM-1 and alpha-MSH expressed by tumor cells were significantly associated with a prolonged relapse-free survival and a longer overall survival." (PMID 32309563, 2015). "Compared with PBMCs and peritumoral tissues, there was an increase in IL-10-producing Bregs in tumor tissues (P < 0.01 or P < 0.05)." (PMID 26378021, 2015). "PBMC or purified monocytes from HNSCC patients co-cultured with tumor cells had increased production of IL-12 p70 (p = 0.02) and decreased production of IL-10 (p = 0.02) in the presence of cetuximab." (PMID 26579227, 2015). "Expression of inflammatory cytokines such as IFN-γ, TNF-α, and IL-2 as well as IL-10 expression in draining lymph nodes (LNs) was significantly reduced in kCYC mice after tumor inoculation." (PMID 26098776, 2015). "Our data demonstrates that a2NTD treatment stimulates neutrophils to overexpress and enhance the secretion of anti-inflammatory mediators such as IL-1RA and IL-10; important mediators in regulating the immune response in tumor site." (PMID 26460736, 2015). "Analysis of macrophage responses to tumor cell conditioned media demonstrates that tumor cell-derived HA stimulates production of IL-10 by macrophages." (PMID 26106384, 2015). "IL-4 induces “alternative” activation of M2-like macrophages; and in response to other cytokines, including TGFβ, IL-10, and CSF-1, this macrophage type has been reported to acquire properties that enhance tumor cell growth, invasion and metastasis." (PMID 27563494, 2015). "Gliomas can upregulate B7-H1 expression in circulating monocytes and tumor-infiltrative macrophages through modulation of autocrine/paracrine IL-10 signaling, resulting in an immunosuppressive phenotype." (PMID 26425658, 2015).
tumor (continued). "It is also worth mentioning that HLA-G expression is highly dependent on tumor microenvironment factors, particular when IL-10 and a hypoxic factor are present." (PMID 25351636, 2015). "Previous studies have shown that tumor associated macrophages express a wide range of molecules, such as TGF-β, arginase-1, EGF, VEGF and IL-10." (PMID 26509874, 2015). "The IL-10 is involved in the function of a number of cells, and influences many physiological processes, including angiogenesis, tumor genesis, and infection." (PMID 26973760, 2015). "The potent anti-inflammatory factor IL-10 induces systemic tumor-specific immunity and plays an important role in the control of tumor-promoting inflammation." (PMID 26457674, 2015). "For instance, TGF-β, IL-10 and IL-17 have been demonstrated to initiate immunosuppressive networks whereas Th1-associated IFN-γ stimulates tumor-specific immunity." (PMID 26350597, 2015). "The function of anti-inflammatory cytokine IL-10 in tumor cells remains controversial as it has both tumor-suppressive and oncogenic roles." (PMID 26056562, 2015). "In mice, tumor cells can induce B cells to produce IL-10, which inhibits CD8+T cells activity and reduces IFN-γ production by CD8+T and NK cells." (PMID 26378021, 2015). "We believe that our study provides significative statistical evidence to declare the important prognostic value of IL–10 as a tumor promoter in cancer patients for the first time." (PMID 26440936, 2015). "It has been well established that several cytokines, including Interleukin-10 (IL-10) and Tumor Necrosis Factor α (TNFα), have a crucial role in a coordinated manner in breast carcinogenesis." (PMID 26112140, 2015). "In contrast, a recent study reported that recombined IL–10 induced tumor rejections by specifically targeting the tumor-infiltrating memory CD8+ T cells to activate the anti-tumor immune response." (PMID 26440936, 2015). "Interleukin-10 (IL-10) is a pleotropic cytokine produced by various types of cells, including T cells, B cells and monocytes, as well as tumor cells." (PMID 26230952, 2015). "A tendency for positive correlation between IL-10 in subcutaneous adipose tissue and in the tumor (p = 0.0978)." (PMID 26732354, 2015). "TGF-β and IL-10 are responsible for the suppression of anti-tumor immune responses and therefore lead to successful tumor escape." (PMID 25767469, 2015). "Several cytokines such as macrophage migratory inhibitory factor (MIF), TNF-α, IL-6, IL-17, IL-12, IL-23, IL-10, and TGF-β have been associated with both experimental and human cancers and can either promote or inhibit tumor development." (PMID 26511466, 2015). "In this study, tumoral protection correlated with lower levels of IL-10 and stronger tumor-specific CD8+ T cells response." (PMID 26042126, 2015). "Accumulating evidence showed that IL–10 played a pleiotropic role in both immune stimulation and suppression in tumor inflammatory microenvironment." (PMID 26440936, 2015). "ROS production by G-MDSCs is known to be induced by several tumor-derived factors such as TGFβ, IL-6, IL-10, and GM-CSF." (PMID 26078490, 2015). "In a nutshell, the immunostimulatory versus immunosuppressive effects of IL-10 marks it as a possible new therapeutic in tumor immunity." (PMID 26556872, 2015). "Both monocytes/macrophages and cancer cells are capable of releasing different pro- and anti-inflammatory cytokines like the immunosuppressive cytokine IL-10, which fosters tumor growth." (PMID 25743773, 2015). "Cytokines with powerful immunosuppressive properties, including TGF-β and IL-10, are known mediators of tumor proliferation, invasion, and immune evasion." (PMID 26217588, 2015). "These important studies provide further in vivo evidence of the tumor suppressor function of this novel member of the IL-10 cytokine gene family." (PMID 26474456, 2015).
tumor (continued). "In contrast, IL-10 levels were significantly reduced in pEEVGmCSF-b7.1-treated mice (both in the spleen and tumour) when compared with the pGT141GmCSF-b7.1-treated group (P<0.05) and all other groups analysed." (PMID 25373914, 2015). "To date, investigations into the role of IL-10 in tumor growth has largely focused on its immunosuppressive actions." (PMID 26217588, 2015). "Our data indicated that circulating CD14+CD169+ M2-like monocytes and TIMs accumulated in the neoplasms and correlated with the levels of plasma IL-10 and CEA in CRC patients." (PMID 26509874, 2015). "Our recent studies indicated that IL-10 is an important regulator which limits NK cell mediated tumor differentiation through inhibition of IFN-γ secretion during monocyte mediated induction of NK anergy (manuscript in prep)." (PMID 25860927, 2015). "Activated NF-κB in tumor cells results in high expressions of immunosuppressive factors such as IL-6, IL-10, TGF-β and VEGF, and impedes the anti-tumor immunity." (PMID 26683520, 2015). "Once in the tumor microenvironment, MDSCs are functionally programmed to be immunosuppressive by the local cytokine profile, with Th2-type cytokines IL-4 and IL-10 driving MDSCs to suppress effector T-cells." (PMID 26690220, 2015). "These immunosuppressors secret TGF-β, IL-10 and other chemokines, result in more immunosuppressive tumor microenvironment." (PMID 26683520, 2015). "Nonetheless, evidence suggests that anti-inflammatory cytokines, such as TGF-β and IL-10, show more complex effects on tumor development." (PMID 24901008, 2014). "Those which have been found to suppress tumor growth include IL-2, IL-12, IL-13 and IFN (gamma, beta and alpha) while IL-4, IL-6, IL-8 and IL-10 predominantly contribute to tumor growth." (PMID 24997057, 2014). "They do so by producing various cytokines, including TGF-, IL-10, and IL-9, thereby promoting tumor growth." (PMID 25356878, 2014). "IL-10 is an immune suppressive cytokine that inhibits the activity of Th1 cells, thus impeding viral clearance and anti-tumor Th1 immunity." (PMID 24624132, 2014). "At the same time, tumor cells can secrete some tumor suppressor factors inhibition of NK cell function, such as IL-10 and TGF-β." (PMID 25299645, 2014). "Here, we showed that GNPs impaired the up-regulation of CD83 by DCs, which is crucial for the stability of their maturation in an IL-10-enriched immunosuppressive tumor micro-environment." (PMID 24802102, 2014). "It has been shown that natural regulatory CD4+ T-cells are highly recruited within the HCC where they secrete IL10 and TGFβ to suppress the antitumor response and promote the tumor growth." (PMID 25525301, 2014). "IL-10 has been shown to contribute in tumor derived immune suppression by suppressing CD4 T cells and inducing myeloid derived suppressor cells." (PMID 25008236, 2014). "We next assessed the relationship between the expression of ILT4 or IL-10 and the number of TILs in all tumor specimens." (PMID 24762057, 2014). "IL-12 has potent anti-tumor effects, based in part on blockade of T regulatory cell secretion of IL-10 and TGF-β." (PMID 24736547, 2014). "Due to its immunosuppressive effect on dendritic cells and macrophages, IL-10 can dampen antigen presentation, cell maturation, and differentiation, allowing tumor cells to evade immune surveillance mechanisms." (PMID 24901008, 2014). "Significant (P < 0.01) decreases of the splenic TNF-α, IL-1β and IL-10 contents were observed in tumor-bearing control mice as compared with intact control mice, respectively." (PMID 25477992, 2014). "In the presence of IL-10, tumor-specific immunity can be activated, but suppression of IL-10 signaling contributes to tumor progression by inhibiting anti-tumor immunity and allowing excessive inflammation that promotes cancer." (PMID 24670367, 2014). "IL-10 is a regulatory cytokine that broadly functions as an immune inhibitory cytokine to support tumor growth." (PMID 25132998, 2014).